MYBL2 (MYB proto-oncogene like 2)
Diseases named in the same sentence as MYBL2 in open-access papers (continued):
Sharing a sentence is not in itself a finding about the gene and the disease.
tumor (continued). "In contrast, tumor promoters such as MYBL2, TYMS, MYC, MCM7, and EGFL7 were downregulated in EF-24–treated cells." (PMID 40986633, 2025). "Other genes, including MYB proto-oncogene like 2 (MYBL2), cyclin dependent kinase inhibitor 2A (CDKN2A), and stathmin 3 (STMN3) were significantly upregulated in tumor tissues from CRC patients and were significantly associated with specific bacterial genera." (PMID 40313460, 2025). "Immunofluorescence analysis demonstrated a significant upregulation of NOTCH3 expression in the tumor tissues of the group with MYBL2 overexpression." (PMID 40092688, 2025). "Various approaches were used to further investigate the role of MYBL2 in immune infiltration within the tumor microenvironment of UCEC." (PMID 40432915, 2025). "Examination of the transplanted tumor tissues revealed that the group with MYBL2 overexpression exhibited marked activation of epithelial-mesenchymal transition (EMT), as evidenced by an upregulation of Vimentin and a downregulation of E-cadherin expression." (PMID 40092688, 2025). "ETS1 and MYBL2 are associated with angiogenesis regulation, with ETS1 regulating VEGF production, crucial for neovascularization and tumor proliferation." (PMID 39912562, 2025). "We observed that the methylation level of the MYBL2 promoter was higher in normal tissues than in primary tumor tissues." (PMID 40432915, 2025). "The study provides evidence for the overexpression of MYBL2 in tumor tissues of UCEC patients and suggests that it can serve as a prognostic marker for patient survival." (PMID 40432915, 2025). "Paired sample analysis of TCGA data further confirmed significantly higher expression of MYBL2 in the tumor group compared to the control group (p = 9.9e-16)." (PMID 40432915, 2025). "While preclinical studies have demonstrated the anti-tumor potential of MYBL2-targeted therapies, including small-molecule inhibitors and CRISPR-based gene editing, challenges persist regarding specificity and off-target effects." (PMID 40432915, 2025). "Our analysis revealed that MYBL2 expression was correlated with immune cell infiltration in multiple tumor contexts." (PMID 40092688, 2025). "In the in vivo tumorigenic study, the MYBL2 knockdown group displayed a substantial decrease in tumor volume (P < 0.01) and exhibited decreased CDCA8 expression in tumors in comparison to the control group." (PMID 38961953, 2024). "We further examined the effects of knocking down MYBL2 on tumor formation in A375 cells through in vivo animal experiments." (PMID 38961953, 2024). "Although E2F1 overexpression significantly increased tumor volume, tumor weight, and tumor growth, these effects were attenuated by MYBL2 knockdown." (PMID 39613162, 2024). "We focused our studies on MYBL2, whose modulation very specifically influenced the functional aspects of metastatic tumour cells." (PMID 39518122, 2024). "In contrast, tumor volume was significantly reduced in mice inoculated with A375 cells with MYBL2 knockdown compared to the group injected with control A375 cells." (PMID 38961953, 2024). "Subsequent investigations revealed that circ-MYBL2 suppressed tumor growth by modifying the phosphorylation levels of the linear MYBL2 isoform." (PMID 39439468, 2024). "E2F7 knockdown led to increases in tumor volume, tumor weight, tumor growth, Ki67-positive cells, and earlier tumor onset, all of which were attenuated by MYBL2 knockdown." (PMID 39613162, 2024). "A syngeneic intraovarian mouse model, flow cytometry analysis, and immunohistochemistry were used to explore the biological function of MYBL2 in tumor progression and immune escape." (PMID 37865750, 2023). "The function of MYB Proto-Oncogene Like 2 (MYBL2) in the tumor microenvironment remains largely unexplored." (PMID 37865750, 2023).
tumor (continued). "in the ShortHER phase III trial found that HER2-enriched BC tumor with mutated PIK3CA had an upregulated expression of MKI67, MYBL2, ESR1, PDCD1 and other genes, but only MYBL2 and PDCD1 were related with a better DFS." (PMID 37313470, 2023). "Mechanistically, we demonstrated that Notch3 prevents tumor initiation via HeyL-mediated inhibition of Mybl2, an important regulator of cell cycle." (PMID 36854682, 2023). "Using a syngeneic intraovarian mouse model, we identified MYBL2 promoted tumor malignancyand increased tumor-infiltrating immunosuppressive macrophages." (PMID 37865750, 2023). "The success of this study will deepen the mechanism that MYBL2 induced tumor progression and provide a new treatment strategy for OVC." (PMID 37865750, 2023). "Cell cycle-related genes such as AURKA, AURKB, GTSE1, CCNA2, and MYBL2 were shown to promote tumor progression of LUAD." (PMID 36304306, 2022). "Other significantly upregulated genes such as SALL4, FOXM1, MYCN, MEP1A and MYBL2 have also been reported to be significantly elevated in HCC and associated with tumor progression." (PMID 36212481, 2022). "A notable tumor-specific event was the downregulation of direct repair (DR) observed in MYBL2 High IDHMUT LGG." (PMID 36358918, 2022). "Across multiple tumor types, elevated MYBL2 expression identified tumors with genomic instability, inefficient HR, and wildtype BRCA." (PMID 36358918, 2022). "The results showed that MYBL2 protein was highly expressed in tumor cells, and a brown granular distribution was observed in the cells and cytoplasm." (PMID 35664780, 2022). "To test if MYBL2 expression identified patients with poor outcomes and progressive disease across tumor types, we analyzed 32 studies curated by The Cancer Genome Atlas (TCGA) and other groups." (PMID 36358918, 2022). "To test if elevated MYBL2 expression identified patients with poor responses to therapy, we analyzed 25 tumor types provided by the Oncology Research Information Exchange Network (ORIEN)." (PMID 36358918, 2022). "MYBL2 High and Low tumors were profiled for tumor-specific genetic driver events as defined previously." (PMID 36358918, 2022). "A2058 cells stably transfected with the MYBL2 shRNA vector were inoculated into male nude mice to observe the effects of MYBL2 KD on tumor growth and progression." (PMID 35664780, 2022). "Across tumor types, we observed strong right-handed tailing indicating that many genes are impacted by gains or heterozygous losses in >30–40% of MYBL2 High tumors." (PMID 36358918, 2022). "While some events were confined to individual tumor types, there was striking conservation of genes altered across MYBL2 High tumors." (PMID 36358918, 2022). "In this study, we provide evidence that elevated MYBL2 expression is a robust marker of poor patient outcomes across tumor types and genotypes." (PMID 36358918, 2022). "Tumor bearing models by HCC cells also exhibited suppression in purine anabolism with MYBL2 knocking out." (PMID 36494680, 2022). "UCSC Xena analysis of the TCGA PRAD dataset (n = 623) showed significant upregulation of FBXO45, SRSF7 and MYBL2 mRNAs in the PCa tumor tissues 50–60% compared to normal." (PMID 35612714, 2022). "KD of MYBL2 in tumor cells strongly inhibited tumor cell growth compared to that in the control group." (PMID 35664780, 2022). "We simultaneously tested the impact of high MYBL2 expression on DREAM formation in our own set of patient-derived tumor samples." (PMID 33747961, 2021). "RT-qPCR confirmed in CC cell lines and tumor tissues the expression of circ-MYBL2, hsa_circ_0075341,hsa_circ_0001038, circRNA8924, circ_0005576, circCLK3, and circ_0018289 was significantly upregulated." (PMID 33841509, 2021). "The in vivo animal model results supported that doxycycline treatment significantly blocked LNCaP-AI/MYBL2-Ri#1-Dox xenograft tumor growth in castrated mice." (PMID 33897882, 2021).
tumor (continued). "To validate these findings, we performed RT-qPCR analysis of MYBL2 expression on our independently collected set of clinical HGSOC tumor samples." (PMID 33747961, 2021). "The growth curve showed that silencing of MYBL2 significantly decreased castration-resistant tumor growth in the hindlimb bone microenvironment." (PMID 33897882, 2021). "To further understand MYBL2 expression by subtype, we applied histological classification of tumor samples." (PMID 33747961, 2021). "Since phospho-Ser/Thr phosphatase cdc25A (CDC25A), cyclin E1 (CCNE1), and Myb-like protein 2 (MYBL2) have been reported as tumour promoters and are known as cell cycle regulators in NSCLC, we focused on these genes." (PMID 33883577, 2021). "We found that MYBL2 is upregulated in the proliferative subtype and in tumor tissue with histologic evidence of proliferation." (PMID 33747961, 2021). "For DFS outcomes, we also found that high MYBL2 expression (HR = 2.00, p = 3.72e–3), age at diagnosis (HR = 1.03, p = 4.95e–3), and high tumor (T) stage (HR = 1.63, p = 1.63e–3) were significantly associated with diminished DFS." (PMID 33489883, 2020). "When analyzing our multivariate OS model results, we found that high MYBL2 expression (HR = 2.50, p = 2.45e–4), age at diagnosis (HR = 1.03, p = 8.51e–3), and high tumor (T) stage (HR = 1.69, p = 1.36e–3) were all significantly associated with diminished OS." (PMID 33489883, 2020). "Recent studies suggest that circulating MYBL2, encoded by the cell-cycle checkpoint gene MYBL2, is detected in AML patients with FLT3-ITD mutations and is closely related to mutant FLT3 expression as well as to tumor cell activity." (PMID 32722298, 2020). "Despite this tight regulation of MYBL2 by EWSR1-FLI1, we noted a marked inter-tumor heterogeneity of MYBL2 mRNA expression in 166 primary EwS and in an independent cohort of 208 EwS on protein level stained for p-MYBL2." (PMID 31511524, 2019). "In line with our transient knockdown experiments, we observed an increased number of stalled mitoses, indicating G2/M blockage, and more apoptotic tumor cells positive for cleaved caspase 3 in MYBL2-silenced xenografts." (PMID 31511524, 2019). "In this study, we show, in the EwS model, how such cooperation steers the expression of the functionally and clinically relevant EWSR1-FLI1 target gene MYBL2, thereby determining tumor growth, patient survival, and drug response." (PMID 31511524, 2019). "More important, T-96 effectively upregulated miR-30e-5p expression, downregulated MYBL2 expression and inhibited tumour growth in a mouse tumour model developed with LN-229 cells." (PMID 30305611, 2018). "More important, T-96 effectively upregulated miR-30e-5p expression and downregulated MYBL2 expression, thus inhibiting LN-229 cell tumour growth in a mouse model." (PMID 30305611, 2018). "We found that MYBL2 and FoxM1 expression had a close correlation with the tumor progression: both genes were higher expression in patients with advanced tumor stage than in normal tissues (*P < 0.05) and early-stage (*P < 0.05)." (PMID 28784180, 2017). "Moreover, MYBL2 demonstrates a significant correlation with immune cell infiltration within the tumor microenvironment (TME) of PCa, with a specific positive association observed with macrophage infiltration." (PMID 40092688, 2025). "EIF4EBP1, as a target gene of the oncoproteins ETS1 and MYBL2, may influence apoptosis by promoting the survival of tumor cells in unfavorable situations." (PMID 39912562, 2025). "Notably, the inhibition of MYBL2 phosphorylation by VEGFR/PDGFR inhibitors can promote tumor growth and survival in VHL disease, which is relevant since VEGFR inhibitors are applied for VHL disease therapy." (PMID 38835346, 2024).
tumor (continued). "Importantly, our data demonstrated for the first time that E2F7 transcriptionally repressed MYBL2 in GC cells and that the tumor suppressive role of E2F7 on GC cells was partly dependent on its transcriptional repression of MYBL2." (PMID 39613162, 2024). "The top TF MYBL2 in the C2 TOP2A+ TCs subgroup is closely linked to tumorigenesis and progression, with studies indicating its association with poor prognosis in different tumor." (PMID 39136009, 2024). "Five transcription factors (CREB1, CTCF, YY1, E2F1, MYBL2) were significantly elevated with tumor progression in HCC, indicating that these potential transcription factors may be responsible for the upregulation of H3–H4 histone chaperones in HCC." (PMID 38561384, 2024). "Circ-MYBL2, as a tumor inhibitor, could repress MM cell proliferation through the circ-MYBL2/Cyclin F/MYBL2 axis." (PMID 38079253, 2024). "In BC patients, a high MYBL2 proto-oncogene level may also be a biomarker of adverse prognosis and could promote tumor invasion by the induction of epithelial–mesenchymal transition (EMT) and modulation of immune microenvironment." (PMID 37313470, 2023). "We measured the tumor volume to determine whether impaired tumor growth upon MYBL2 knockdown was a consequence of reduced macrophage recruitment." (PMID 37865750, 2023). "All MYBL2 High tumor cohorts exhibited greater levels of microsatellite instability (MSI)." (PMID 36358918, 2022). "To understand the specific function of MYBL2 in HCC, we generated functional knockout of MYBL2 by CRISPR/Cas9 system in HepG2 cells, and implanted the MYBL2 knockout and parental cells in the flanks of NSG mice for 3 weeks, tumor growth were retarded after loss of MYBL2." (PMID 36494680, 2022). "Lastly, analysis of tumor hypoxia scores revealed MYBL2 High tumors are significantly hypoxic." (PMID 36358918, 2022). "Then we evaluated the expressions of LINC00346, miR-30c-2-3p and MYBL2 in tumor tissues by qRT-PCR." (PMID 34631522, 2021). "A previous study indicated that MYBL2 acted as one oncogene in tumour development." (PMID 33787061, 2021). "Similarly, MYBL2 exhibited higher expression in HGSOC tumor samples than healthy ovarian surface epithelium controls." (PMID 33747961, 2021). "Importantly, administration of Simvastatin or Verteporfin resulted in persistent suppression of castration-resistant tumor growth in MYBL2 high-expressing LNCaP tumor xenografts." (PMID 33897882, 2021). "Importantly, MYBL2 knockdown significantly reduced the incidence of bone metastasis (from 62.5% to 12.5%) and the number of bone metastatic lesions (from 2 to 0.25) in tumor-bearing mice." (PMID 33897882, 2021). "Previous studies reported that FOXM1, ERG, and MYBL2 played a role in tumor immune infiltration." (PMID 34489925, 2021). "Importantly, doxycycline treatment resulted in reduced expression of Ki67 and an increased percentage of apoptotic cells in LNCaP-AI/MYBL2-Ri#1-Dox tumor xenografts compared with that in the vehicle-treated groups." (PMID 33897882, 2021). "Of the top 12 transcriptional regulators, CENPA, FOXM1, and MYBL2 were among the most highly expressed and displayed the largest differences in expression between tumor and normal tissues; each was >8 times more highly expressed in LUAD as compared to normal lung." (PMID 32925947, 2020). "Moreover, the expression level of MYBL2 was positively correlated with the classification and staging of tumours." (PMID 30305611, 2018). "Tumor and non-tumor samples differed significantly in the expression of 10/22 genes: CCNB1, CLDN4, CLDN6, MMP2, MUC1 (all: p < 0.05), BAG1, SERPINB3 (all: p < 0.01), CD44 (standard variant), MKI67, and MYBL2 (all: p < 0.001)." (PMID 27542596, 2016). "Importantly we found the same correlative changes in MMB/DREAM complex component expression in the microarray analysis of an independent set of OAC samples, although the overexpression of MYBL2 in these tumours was less marked." (PMID 25889361, 2015).
tumor (continued). "Hence, our finding establishes MYBL2 as a key tumor suppressor gene of the 20q CDR affected in human MDS and MPD." (PMID 23878725, 2013). "Additionally, the underlying molecular mechanisms by which MYBL2 influences tumor progression and immune evasion are not fully elucidated, requiring functional studies to bridge this gap." (PMID 40432915, 2025). "MYBL2 plays a significant role in cell viability, cell cycle progression, and cellular differentiation, implying that malfunction of MYBL2 may contribute to the progression and initiation in tumor." (PMID 38961953, 2024). "NOTCH2NL, MYBL2, and UBE2T were reported to be involved in tumorigenesis, while CXCR4 and IL18R1 were associated with immune response and pathway activation, indicating SRSF1 may take part in MM progression via tumor-related pathways." (PMID 37206090, 2023). "Finally, the relationships between MYBL2 expression and other biomarkers of ICB, such as the tumor mutation burden, remain unknown." (PMID 37865750, 2023). "However, our syngeneic intraovarian mouse models demonstrated that MYBL2 failed to induce intratumoral and ascitic trafficking of TAMs and facilitated tumor progression upon LC treatment, indicating that the tumor-promoting mechanisms of MYBL2 largely depended on TAMs." (PMID 37865750, 2023). "Therefore, circ-MYBL2 may downregulate miR-19a through methylation pathways to play tumor suppressive roles, while the methylation factors involved in this process remain to be identified." (PMID 35387554, 2022). "Furthermore, we believe these findings are likely to have clinical ramifications since aberrant regulation of MYBL2 may affect the sensitivity of tumour cells to inhibitors of the ATM‐dependent DNA damage response." (PMID 33779025, 2021). "However, it remains to be determined what regulates the expression of MYBL2 and whether MYBL2 could be a novel anti-tumor target." (PMID 28286417, 2017). "Indeed, tumours expressed higher Mybl2 RNA levels and exhibited increased B-Myb phosphorylation." (PMID 28248314, 2017). "Frau and colleagues also indicated that MYBL2 upregulation could induce fast growth and progression of premalignant and malignant liver, through cell cycle deregulation and activation of genes and pathways related to tumor progression." (PMID 25424347, 2014). "Functionally, MYBL2 overexpression enhanced the proliferation, migration, and invasion of LSCC cells in vitro and promoted tumor growth in vivo." (PMID 41866755, 2026). "Tumor-related genes TRPM4, MYBL2, and CDKN2A were significantly upregulated and correlated with specific bacterial taxa." (PMID 40313460, 2025). "miR-143-3p acts as a tumor suppressor by regulating LIMK1 and MYBL2, inhibiting cell cycle progression and metastasis in TNBC." (PMID 41009685, 2025). "Eight genes exhibited greater than 340-fold increases in expression in tumor tissues (CLDN6, KLK7, WNT10A, MYBL2, MAL2, KRT7, PRSS8, EPCAM; Median (Range) of fold increase = 344 (261–7267))." (PMID 41465326, 2025). "MYBL2 and RAD54L have been demonstrated to be downstream targets of E2F1, which has been demonstrated to be involved in tumor growth and metastasis." (PMID 38424195, 2024). "To evaluate the effects of MYBL2 knockdown on E2F1 overexpression or E2F7 knockdown in a more physiologically relevant setting, we performed tumor xenograft assays using genetically modified AGS sublines generated using the Tet-On system." (PMID 39613162, 2024). "The tumor response to hypoxia conditions is mediated by MYB and MYBL2 and their interaction with the ubiquitin ligase protein of the von Hippel-Lindau (pVHL) gene and hypoxia-inducible factors (HIFs)." (PMID 38835346, 2024). "The outcome revealed a notable decrease in tumor volume and CDCA8 protein expression in tumors in the MYBL2 knockdown group in comparison to the findings in the control group." (PMID 38961953, 2024).